HAS3 (hyaluronan synthase 3)
Diseases named in the same sentence as HAS3 in open-access papers (continued):
Sharing a sentence is not in itself a finding about the gene and the disease.
glioma (6 papers, 2019 to 2024). A benign or malignant brain and spinal cord tumor that arises from glial cells (astrocytes, oligodendrocytes, ependymal cells). "Beside HA and CD44 upregulation, human glioma tissues display high level of hyaluronic acid synthase 3 (HAS3), which negatively correlated with the prognosis glioma patients." (PMID 38969910, 2024). "Silencing HAS3 expression or blocking CD44 slowing down glioma cell proliferation, through the inhibition of autophagy and cell cycle arrest in G1 phase." (PMID 38969910, 2024). "This evidence further suggests that autophagy flux is blocked after HAS3 silencing or the binding of HA to CD44 receptors is inhibited in glioma cells." (PMID 33986244, 2021). "Inhibition of HAS3 or treatment with the CD44 antibody combined with autophagy inhibitors exerted synergistic inhibitory effects on glioma proliferation through a molecular mechanism that involves arresting the cell cycle in G1 phase." (PMID 33986244, 2021). "The inhibition of HAS3 or CD44 in vivo significantly decreased the glioma volumes, extended the survival time of mice, and downregulated Ki67 expression compared with controls." (PMID 33986244, 2021). "HAS3 silencing or treatment with the CD44 antibody increased the number of autophagic vesicles in glioma cells." (PMID 33986244, 2021). "HAS3 silencing or treatment with the CD44 antibody combined with CQ exerted a synergistic effect on reducing the viability of glioma cells and levels of the Ki67 protein." (PMID 33986244, 2021). "We next explored the effects of interfering with HA metabolism mediated by inhibiting HAS3 or CD44 on glioma progression." (PMID 33986244, 2021). "Silencing HAS3 expression or blocking CD44 inhibited glioma cell proliferation in vitro and in vivo." (PMID 33986244, 2021). "They showed the expression of all three HAS isoforms in mesothelial cells, only HAS3 in mesothelioma cells, and HAS2 and HAS3 in both lung fibroblasts and glioma cell line." (PMID 30875861, 2019). "Our previous results confirmed that HAS3 overexpression could accelerate HA synthesis in glioma and thus promote glioma malignant progression." (PMID 37568202, 2023). "Therefore, we investigated the effect of silencing HAS3 or treatment with CD44 antibodies on glioma cell cycle arrest." (PMID 33986244, 2021). "Moreover, inhibition of HAS3 or treatment with the CD44 antibody decreased the expression of Ki67 in U251 or LN229 glioma cells, respectively." (PMID 33986244, 2021). "We transfected the HAS3 siRNA or added CD44 antibody to U251 glioma cells to test this hypothesis." (PMID 33986244, 2021). "Moreover, in view of HAS1, HAS2, and HAS3 expression in glioma, we over-expressed HAS1 and knocked down HAS2 in glioma cell lines, the results demonstrated the over-expression of HAS1 or the silencing of HAS2 did not significantly affect the viability of glioma cells." (PMID 33986244, 2021). "A recent study by Yan and his colleagues in 2021 shed light on this aspect, demonstrating heightened expression levels of HA, hyaluronic acid synthase 3 (HAS3), and the HA receptor CD44 correlated inversely with the prognosis of glioma patients." (PMID 38732975, 2024). "HAS3 and CD44 expression were significantly decreased in glioma cells transfected with the HAS3 siRNA and CD44 siRNA, respectively, compared with control glioma cells." (PMID 33986244, 2021). "Next, we established stable U251 cell lines with knockdown of HAS3 and CD44 to further analyze the effects of HAS3 and CD44 on glioma cell viability and proliferation in vivo." (PMID 33986244, 2021). "First, the relative expression of HA, HAS3, and CD44 were determined in five glioma cell lines (LN229, U251, U87, T98, A172) and HUVEC cells." (PMID 33986244, 2021). "The results confirmed the relative expression levels of HA, HAS3, and CD44 in glioma were higher than those in HUVEC cells." (PMID 33986244, 2021).
glioma (continued). "More importantly, silencing HAS3 or treatment with the anti-CD44 antibodies decreased the levels of the cell cycle-related proteins cyclin B1 and cyclin D1 in glioma cells, and CQ treatment further enhanced this effect." (PMID 33986244, 2021). "To further verify the pro-survival effect of HAS3 and CD44, we over-expressed HAS3 and CD44 in glioma cell lines." (PMID 33986244, 2021). "Our previous study confirmed that the expression of hyaluronan synthase 3 (HAS3) and CD44 is elevated in gliomas; on the one hand, increased HAS3 expression can promote HA biosynthesis, and on the other hand, overexpressed CD44 can combine with HA to accelerate glioma progression." (PMID 37568202, 2023). "HA synthesis was inhibited by HAS3 silencing in U251 and LN229 glioma cell lines." (PMID 33986244, 2021). "Notably, siRNAs were used to silence HAS3; alternatively, CD44 antibody was added to the culture media of glioma cells." (PMID 33986244, 2021). "The present study indicated that HA, hyaluronic acid synthase 3 (HAS3), and a receptor of HA named CD44 were expressed at high levels in human glioma tissues and negatively correlated with the prognosis of patients with glioma." (PMID 33986244, 2021). "Alterations in HA metabolism induced by silencing HAS3, blocking its binding with the receptor CD44, or administering 4-MU inhibited autophagy flux, arrested the cell cycle at G1 phase, and subsequently inhibited glioma cell proliferation in the present study." (PMID 33986244, 2021). "Thus, approaches that interfere with HA metabolism by altering the expression of HAS3 and CD44 and the administration of 4-MU potentially represent effective strategies for glioma treatment." (PMID 33986244, 2021). "Overall, HA, HAS3, and CD44 levels are significantly increased in glioma tissues and may play important roles in glioma progression." (PMID 33986244, 2021). "Overall, the inhibition of HAS3 and CD44 decreased glioma cell proliferation in vitro and in vivo." (PMID 33986244, 2021). "Therefore, HAS3 and CD44 were chosen for further analysis of HA metabolism in glioma." (PMID 33986244, 2021). "Therefore, we speculated that it is highly likely that the overexpression of HAS3 promotes the abnormal biosynthesis of HA, and then excess accumulated HMW-HA can be further degraded into LMW-HA by HYAL2, which ultimately accelerates the malignant progression of glioma." (PMID 37568202, 2023). "One possible explanation is that HAS3 and CD44 are already highly expressed in gliomas, and therefore, increasing their expression has no obvious effect on glioma proliferation." (PMID 33986244, 2021).
lung carcinoma (6 papers, 2011 to 2024). "We aimed to cross-validate these findings on human and murine lung cancer cells and observed that CD133 + CSC differentially expressed higher levels of HA, HAS3, ABCC5, SOX2, and CD47 (p < 0.01)." (PMID 39039104, 2024). "Induction of HAS3 expression by EGF and ErbB2 receptors has also been shown for keratinocytes, prostate and lung carcinoma cells." (PMID 21429221, 2011). "A previous study studying HA CD44/RHAMM pathway in lung cancer cells only knocked down HAS2 and HAS3 as us, we suggested they might also come across the same issue." (PMID 33407495, 2021). "We determined the expression level of HAS2, HAS3, CD44, and RHAMM in lung cancer cell lines except for CD44 in H1975 and HAS2 in H460 which might be too low to be detected in our experiment." (PMID 33407495, 2021). "Moreover, genome-wide transcript analysis of tumor samples confirmed a close correlation between ZEB1 and HAS2 (but not with HAS1 and HAS3) in breast, pancreas and lung cancer specimens (GSE42568, GSE28735 and GSE41271)." (PMID 28086235, 2017).
cardiomyopathy (5 papers, 2019 to 2025). A disease of the heart muscle or myocardium proper. "These analyses identified a SNP in hyaluronan synthase 3 (HAS3) that was associated with high doses of anthracyclines treatment was significantly associated with cardiomyopathy." (PMID 38989148, 2024). "A two-stage study revealed the variant, rs2232228, in the hyaluronan synthase 3 (HAS3) gene with a modifying effect on the anthracycline dose-dependent cardiomyopathy risk." (PMID 30832275, 2019). "In addition, exposition to anthracycline doses >250 mg/m2 and carrying at least one A allele in the HAS3-rs2232228 variant were at increased risk of cardiomyopathy compared to the GG genotype (AA: p = 0.003 and AG: p = 0.02)." (PMID 40413218, 2025). "Most research was done on doxorubicin-induced cardiomyopathy and for seven genetic variants in CELF4, GPR35, HAS3, RARG, SLC22A17, SLC22A7 and SLC28A3, replication studies were performed without consistent results." (PMID 36536332, 2022). "No variants were associated with anthracycline-induced cardiomyopathy, but a gene-environment interaction analysis identified the variant HAS3 rs2232228." (PMID 36536332, 2022).
colitis (5 papers, 2015 to 2019). Inflammation of the colon. "We compared the disease progression and histological changes in the colon over the ten-day time course of disease and found that mice that carried the HAS3 null mutation had much less severe colitis by every means of analysis." (PMID 26448758, 2015). "Our data on the down-regulation of Has3 mRNA and the reduction of fibrosis and inflammation is consistent with previous animal studies in lung and colitis model." (PMID 30858465, 2019). "In this study, we tested the progression of inflammation in mice null for the hyaluronan synthase genes (HAS1, HAS3, or both HAS1 and HAS3) in the DSS-colitis model." (PMID 26448758, 2015). "Weight loss, disease activity, colitis scoring, circulating IL-6 levels, and histology/immunostaining were all ameliorated in HAS3 null mice experiencing colitis." (PMID 26448758, 2015). "Indeed, in the DSS-induced colitis model, HAS3 expression is predominantly localized to the endothelial cells found in gut microvessels where it produces a leukocyte-adhesive HA and contributes to inflammation." (PMID 27042213, 2016). "Our data demonstrate that both the HAS1/HAS3 double and the HAS3 null mice are protected from colitis, compared to wild-type and HAS1 null mice, as determined by measurement of weight loss, disease activity, serum IL-6 levels, histologic scoring, and immunohistochemistry." (PMID 26448758, 2015). "Developing a temporary targeted therapeutic intervention of HAS3 expression or function in the microcirculation may emerge as a desirable strategy toward tempering colitis in patients undergoing flares of IBD." (PMID 26448758, 2015). "To test our hypothesis that HA is a key molecule that drives inflammation in the gut during intestinal inflammation, we treated mice that were null for either HAS1 or HAS3 or both HAS1/HAS3 in the experimental DSS-colitis model." (PMID 26448758, 2015). "To determine whether perturbing HA production could change the course of colitis, we outbred the HAS1/3 double null mice with wild-type, background matched c57B/6 mice to generate the single HAS1 or HAS3 null strains used in the current DSS-colitis model study." (PMID 26448758, 2015). "The HAS3 null group, similar to the HAS1/3 double null cohort, was far less affected by DSS-induced colitis." (PMID 26448758, 2015). "The HAS3 null mice have the lowest DAI, the lowest colitis score, and the lowest circulating levels of the proinflammatory cytokine IL-6, compared to the wild-type, HAS1 null, and HAS1/3 null groups." (PMID 26448758, 2015). "HAS3 null mice exhibit decreased intestinal inflammation and tissue damage in the DSS-induced colitis model compared to wild-type, HAS1 null, and HAS1/3 double null mice while mice lacking HAS1 exhibit heightened HA deposition in both the lamina propria and submucosa during induced colitis." (PMID 26448758, 2015). "At day 10 time point, the difference is even more pronounced and demonstrates the decrease in colitis severity when the HAS3 enzyme is absent, both in the HAS3 null and the HAS1/3 null groups." (PMID 26448758, 2015). "We experimentally tested whether disrupting HA production affects the inflammation process that occurs in the murine DSS-colitis model, using HAS1 null, HAS3 null, and HAS1/HAS3 double null mice." (PMID 26448758, 2015). "In the current work we found that deletion of one of the HA synthesizing enzymes, specifically HAS3, but not HAS1, significantly reduced the course of colitis in mice." (PMID 26448758, 2015).
pancreatic cancer (5 papers, 2014 to 2025). "To further validate the broad applicability of CAF-targeted HA degradation across diverse tumor types, we assessed TAVO423 in a pancreatic cancer model employing BxPC-3 cells engineered to overexpress hyaluronan synthase 3 (BxPC-3-HAS3)." (PMID 41228205, 2025). "Knockdown of PTEN resulted in a significant increase in HAS3, which has previously been shown to promote tumor growth in pancreatic cancer." (PMID 30456390, 2018). "Elevated HAS3 expression promoted the growth of prostate, colon and pancreatic cancer cells and angiogenesis in prostate cancer." (PMID 28107185, 2017). "In conclusion, hyaluronan accumulation by HAS3 favors pancreatic cancer growth, at least in part by decreasing epithelial cell adhesion, and PEGPH20 inhibits these changes and suppresses tumor growth." (PMID 25147816, 2014). "In this study, we explored the biological consequences of HAS2 and HAS3 overexpression in BxPC-3 pancreatic cancer cells and in xenograft tumor models." (PMID 25147816, 2014). "Furthermore, analysis of The Cancer Genome Atlas indicated that increased HAS3 expression correlated with decreased survival in pancreatic cancer patients." (PMID 30456390, 2018). "Overexpression of HAS3 increased hyaluronan synthesis in BxPC-3 pancreatic cancer cells." (PMID 25147816, 2014). "In contrast to a potential oncogenic role of HAS enzymes in carcinogenesis, HAS3 under-expression was a poor prognositic marker for bladder cancer and the promoter methylation of HAS3 was recently proposed to regulate hyaluronan production in pancreatic cancer." (PMID 28107185, 2017). "HAS2 and HAS3 were found to produce extracellular HA, and HAS2 appears to contribute to cytoplasmic HA production when HAS2 is overexpressed in pancreatic cancer cells." (PMID 29137675, 2017).
breast tumor (4 papers, 2020 to 2024). "The IHC staining results indicated that the HAS3 protein expression was lower in human breast tumor tissues than the adjacent normal tissues." (PMID 34770956, 2021). "Since several prometastatic genes (Plau, Mmp2, Mmp9, Has2, and Has3) were downregulated in Mbd2-KO PyMT tumors, we next used formalin-fixed lung tissue sections collected at the experimental endpoint and stained them with hematoxylin and eosin (H&E) to assess breast tumor metastasis to the lung." (PMID 38556549, 2024). "Alterations in HAS1 (< 2%) and HAS3 (6%) were rare, suggesting that HAS2 is the most relevant HA synthase in breast tumors." (PMID 32774770, 2020). "This study demonstrated that the hyaluronic acid synthase 3 (HAS3) protein and its enzymatic product hyaluronic acid (HA) encompassed in the subcutaneous extracellular matrix can attenuate the invasion of human breast tumor cells." (PMID 34770956, 2021). "The growth rate of breast tumors increased significantly in mice lacking HAS3 compared with wild-type mice (* p< 0.05)." (PMID 34770956, 2021).
atherosclerosis (3 papers, 2020 to 2025). A disease characterized by the build-up of fatty material and calcium deposition in the arterial wall resulting in partial or complete occlusion of the arterial lumen. "This contrasts with a model of atherosclerosis, where Has3 loss led to an ECM-producing SMC phenotype - replicated in vitro by CD44 blocking - and was linked to increased plaque stability." (PMID 41280888, 2025). "Moreover, a recent study using Has3/ApoE double deficient mice clearly demonstrated that Has3-mediated HA synthesis was critical in the development of atherosclerosis." (PMID 33171800, 2020).
colorectal cancer (3 papers, 2013 to 2020). A primary or metastatic malignant neoplasm that affects the colon or rectum. "We then selected the 4 colorectal cancer-related genes ADM, DKK1, HAS3 and SMURF2 for quantitative real-time PCR verification." (PMID 23922913, 2013).
head and neck squamous cell carcinoma (3 papers, 2011 to 2024). A squamous cell carcinoma that arises from any of the following anatomic sites: lip and oral cavity, nasal cavity, paranasal sinuses, pharynx, larynx, and salivary glands. "We have previously demonstrated that in head and neck squamous cell carcinoma (HNSCC) ΔNp63 controls the expression of the HA-related genes HAS3, HYAL1, and CD4446." (PMID 30139970, 2018). "Therefore, EGF may be an important regulator of HAS3 expression in ESCC, which would be especially relevant in cancers known to be responsive to EGF inhibition, such as head and neck squamous cell carcinoma and metastatic colorectal cancer." (PMID 21429221, 2011).
neuroblastoma (3 papers, 2019 to 2022). Neuroblastoma (NB) is the most common solid, extracranial childhood tumor. "Melatonin promotes the differentiation of neuroblastoma cells by activating cell phagocytosis induced by hyaluronate synthase 3 (HAS3)." (PMID 35408534, 2022). "Our previous study demonstrated that forced-induced HAS3 overexpression in neuroblastoma formed abnormal cristae." (PMID 34770956, 2021). "Our previous study demonstrated that serum starvation significantly induced neuroblastoma (N2a) cancer cell differentiation through the HAS3 protein expression." (PMID 34770956, 2021). "This study provides the molecular basis for a novel pathway of neuroblastoma differentiation in which melatonin treatment upregulates HAS3." (PMID 31274246, 2019). "Our study provides a molecular basis for understanding the mechanisms by which melatonin prevents the initiation of neuroblastoma cell growth via the activation of HAS3‐mediated cellular differentiation." (PMID 31274246, 2019). "In summary, our data demonstrate that physiological concentrations of melatonin can prevent tumors and may be able to eliminate early‐stage neuroblastoma (N2a) cells by upregulating the HAS3 protein and triggering differentiation." (PMID 31274246, 2019).